CBLL1 (Cbl proto-oncogene like 1)
Description:
E3 ubiquitin-protein ligase that mediates ubiquitination of several tyrosine-phosphorylated Src substrates, including CDH1, CTTN and DOK1 (By similarity). Targets CDH1 for endocytosis and degradation (By similarity). Associated component of the WMM complex, a complex that mediates N6-methyladenosine (m6A) methylation of RNAs, a modification that plays a role in the efficiency of mRNA splicing and RNA processing. Its function in the WMM complex is unknown.
Synonyms: HAKAI; RNF188; FLJ23109
Tractability: PROTAC: ubiquitination databases record sites on it; its protein half-life has been measured.
Gene: Protein-coding gene on chromosome 7 (107,743,073 to 107,761,667, forward strand). Ensembl gene ENSG00000105879.
Subcellular location: Nucleus speckle; Nucleus, nucleoplasm; Cytoplasm
Subcellular location (Human Protein Atlas): Nuclear speckles
Pathways (Reactome):
Cell-Cell communication: Degradation of CDH1; SRC activates STAT3 in a quantitative manner, through Cadherin-11 (CDH11), RAC1 and gp130 (IL6ST)
Disease: InlA-mediated entry of Listeria monocytogenes into host cells
Gene Ontology:
Molecular function: protein binding; ubiquitin protein ligase activity; ubiquitin-protein transferase activity; identical protein binding
Biological process: cell-cell adhesion; mRNA processing; negative regulation of cell adhesion; positive regulation of cell migration; positive regulation of endocytosis; protein ubiquitination; regulation of cell adhesion
Cellular component: nuclear speck; RNA N6-methyladenosine methyltransferase complex; cytoplasm; cytosol; nucleus; ubiquitin ligase complex; nucleoplasm
Genetic constraint (gnomAD): Loss-of-function variants: 3 observed, 30.95 expected, observed/expected ratio (o/e) 0.0969, 90% interval 0.043 to 0.25. The upper end of that interval is the gene's LOEUF score, 0.25, which puts it in group 1 of 6, group 1 being the genes least tolerant of losing a copy. Missense variants: 473 observed, 560.16 expected, observed/expected ratio (o/e) 0.84, 90% interval 0.78 to 0.91. Synonymous variants: 203 observed, 179.31 expected, observed/expected ratio (o/e) 1.13, 90% interval 1.01 to 1.27.
Homologues: Orthologues: chimpanzee CBLL1 (100% identical), macaque CBLL1 (99% identical), pig CBLL1 (98% identical), dog CBLL1 (97% identical), mouse Cbll1 (97% identical), rat Cbll1 (97% identical), tropical clawed frog cbll1 (83% identical), zebrafish cbll1 (67% identical), guinea pig CBLL1 (53% identical), Drosophila melanogaster Hakai (24% identical). Paralogues in human: CBLL2 (44% identical).
Diseases named in the same sentence as CBLL1 in open-access papers:
CBLL1 is named in the same sentence as 35 diseases in open-access papers, as found by Europe PMC text mining. Sharing a sentence is not in itself a finding about the gene and the disease. The quoted sentences say what the papers report.
breast carcinoma (8 papers, 2017 to 2025). "High CBLL1 gene expression was associated with a better prognosis in patients with breast cancer, and functional analysis revealed its involvement in the regulation of multiple pathways, including apoptosis, the ESR1-pathway, and immune response." (PMID 39833727, 2025). "Conversely, the prognostic value of CBLL1 gene expression in breast carcinomas was analyzed alongside that of other m6A regulators." (PMID 39833727, 2025). "However, CBLL1 mRNA expression was higher (samples 83.3% ER positive) in these breast cancers than in adjacent tissues." (PMID 34044876, 2021). "CBLL1, as an E3 ubiquitin protein ligase, competes with ERa coactivators and plays a negative role in the development and progression of breast cancers." (PMID 34044876, 2021).
non-small cell lung carcinoma (5 papers, 2020 to 2022). A group of at least three distinct histological types of lung cancer, including non-small cell squamous cell carcinoma, adenocarcinoma, and large cell carcinoma. "CBLL1 has been reported to be overexpressed and associated with poor prognosis in non-small cell lung cancer (NSCLC) and esophageal cancer (EC)." (PMID 35223847, 2022). "CBLL1 expression is markedly elevated in gastric, colon and non-small cell lung cancers (NSCLC), suggesting a pro-oncogenic role." (PMID 36733939, 2022). "In addition, circ_0072083 could promote cell proliferation, migration and invasion via regulating miR-101-3p/cullin 4B (CUL4B), and facilitated cisplatin resistance via regulating miR-545-3p/Cbl proto-oncogene like 1 (CBLL1) in non-small cell lung cancer." (PMID 33975615, 2021). "Cbl Proto-Oncogene Like 1 (CBLL1), an E3 ubiquitin ligase with a RING-finger domain, was found to have an upper expression in non-small-cell lung cancer tissues and was identified to be involved in the cell cycle and colony formation." (PMID 36468034, 2022).
colon carcinoma (4 papers, 2021 to 2025). "CBLL1 was correlated with the N stage, combined with the qPCR results showing that low CBLL1 expression in highly metastatic cell lines, indicates that CBLL1 is related to colon tumor metastasis, while ALKBH5 is associated with T and N stages." (PMID 33670062, 2021). "Taken together, our results underscore the potential use of CBLL1 gene expression as a novel biomarker for CMS2 tumour samples in colon cancer patients." (PMID 38339195, 2024). "Similarly, the same association as CBLL1 was found for the LGR5 gene, a cancer stem cell biomarker in colon cancer, as well as with the transcription factor c-MYC, which is a well-known universal marker of CSCs." (PMID 38339195, 2024). "In support of these results, by using ultra-low attachment plates and a specific medium to enrich cancer stem cells, we grow 3D tumourspheres of colon cancer stem cells and find high mRNA levels of CBLL1, LGR5, and c-MYC compared to those levels in 2D monolayer cell cultures." (PMID 38339195, 2024).
prostate carcinoma (4 papers, 2021 to 2024). A carcinoma that arises from epithelial cells of the prostate gland. "Compared with normal tissues, the content of CBLL1 in prostate cancer tissues was lower, and its expression has an adverse effect on the development and prognosis of prostate cancer." (PMID 34899855, 2021). "Premised on the expression of CBLL1, we also identified potential therapeutic agents for prostate cancer, and knockdown of FTO prominently inhibited prostate cells migration and invasion in vitro experiment." (PMID 34899855, 2021). "CBLL1 also has a superior ability to predict survival in prostate cancer patients." (PMID 34899855, 2021). "High levels of METTL3 and CBLL1 could predict the poor prognosis of prostate cancer patients." (PMID 36835633, 2023). "Subsequently, we determined CBLL1, FTO, YTHDC1, HNRNPA2B1 as crucial m6A regulators of prostate cancer." (PMID 34899855, 2021). "The expression of METTL3, METTL14, WTAP, and CBLL1 was higher in prostate cancer cells compared to non-malignant prostate cells." (PMID 36835633, 2023).
periodontitis (3 papers, 2021 to 2023). An acute or chronic inflammatory process that affects the tissues that surround and support the teeth. "CBLL1 is related to several immune reactions, and especially cytokine has been reported taking part in periodontitis progress and has essential and pleiotropic impacts on the recruitment of specific immunocytes, control of pathobionts and induction or suppression of osteoclastic activity." (PMID 33724691, 2021). "The transcriptome relationships were investigated, and we found there are close correlations among writers, readers and erasers; the CBLL1 and YTHDC2 are the most correlated m6A regulators in expression both in all samples and periodontitis samples, indicating that they function together." (PMID 33724691, 2021).
bladder cancer (2 papers, 2022). "Elevated CBLL1 and WTAP expression in PCa compared with non-malignant prostate cells is consistent with results observed in other cancer types where higher CBLL1 expression has been reported in HCC and NSCLC, with elevated WTAP expression found in bladder cancer and AML." (PMID 36733939, 2022).
cervical cancer (2 papers, 2022). A primary or metastatic malignant neoplasm involving the cervix. "Subsequent gene interaction network analysis indicated that 3 genes (ZC3H13, METTL14, and CBLL1) appeared to serve as network hubs, suggesting that dysregulation of m6A modification by these genes provided major contributions to the development and/or progression of cervical cancer." (PMID 35418160, 2022).
colorectal cancer (2 papers, 2018 to 2024). A primary or metastatic malignant neoplasm that affects the colon or rectum. "In this study, by using robust bioinformatics and machine learning methods, we provide evidence that high CBLL1 mRNA expression is specifically associated with consensus molecular subtype 2 (CMS2) in colorectal cancer patients, which is characterised by strong activation of the WNT and MYC pathways." (PMID 38339195, 2024). "In conclusion, we propose CBLL1 as a new biomarker gene for the stratification of CMS2 colorectal cancer patients." (PMID 38339195, 2024). "In this study, we show that the CBLL1 gene is a biomarker for CMS2 colorectal cancer, as we demonstrate a significant upregulation in this molecular subtype of CRC." (PMID 38339195, 2024). "Considering these results together, we highlight the potential use of CBLL1 as a biomarker of CMS2 colorectal cancer patients and its implication of in the cancer stem cell tumoursphere." (PMID 38339195, 2024). "We postulate that CBLL1 is a new biomarker gene for the stratification of CMS2 colorectal cancer patients and has a well-defined prognostic value in this cohort of patients." (PMID 38339195, 2024). "Taken together, these findings suggest that CBLL1 is emerging as a potential biomarker for a specific subtype of colorectal cancer tumours and may help to stratify patients based on comparative survival analysis." (PMID 38339195, 2024). "For example, CBLL1, or HAKAI, is a proto-oncogene implicated in colorectal cancers." (PMID 29971090, 2018).
endometriosis (2 papers, 2022 to 2023). The growth of functional endometrial tissue in anatomic sites outside the uterine body. "Endometriosis patients with a high expression of CBLL1 and METTL3 showed a notably high expression level of ALKBH5." (PMID 36672827, 2022).
lung carcinoma (2 papers, 2021 to 2023). "The expression of CBLL1 expression was upregulated in lung cancer and BC compared with adjacent tissues." (PMID 33926554, 2021). "CBLL1 expression correlated with poor prognosis in lung cancer." (PMID 33926554, 2021). "For example, ZC3H13, CBLL1, ELAVL1, and YTHDF1 are differentially expressed in lung cancer tissues, which is significant for predicting and treating lung cancer." (PMID 37938417, 2023).
sarcoma (2 papers, 2022). A usually aggressive malignant neoplasm of the soft tissue or bone. "Although there is no report on the correlation between the expression of RP11-283I3.6 and CBLL1 and SARC progression, based on our results, we speculate that they may be potential biomarkers for sarcoma prognosis." (PMID 36313417, 2022). "The expression levels of Cbl-like 1 (CBLL1) and IGF2BP2 in normal and sarcoma tissues were not statistically significant." (PMID 34979500, 2022).
Breast Invasive Carcinoma (1 paper, 2025). "Within the TCGA Breast Invasive Carcinoma PanCancer Atlas dataset (n = 996) mutations of METTL3, METTL14 and CBLL1 were uncommon, with amplifications being the most common genetic alteration." (PMID 41310336, 2025).
COVID-19 (1 paper, 2022). A disease caused by infection with severe acute respiratory syndrome coronavirus 2. "COVID-19 patients with elevated expression levels of CBLL1, METLL16, and RBM15B presented elevated expression levels of ALKBH5 while elevated METTL14 and ZC3H13 expression demonstrated a negative association with ALKBH5." (PMID 35655464, 2022).
dengue (1 paper, 2015). "E3 ubiquitin ligase, CBLL1 (HAKAI) has been found to be important during WNV endocytosis, but not in dengue entry." (PMID 26325027, 2015).
epilepsy (1 paper, 2022). A brain disorder characterized by episodes of abnormally increased neuronal discharge resulting in transient episodes of sensory or motor neurological dysfunction, or psychic dysfunction. "The random forest (RF) model was applied to the screening, and seven m6A regulators (HNRNPC, WATP, RBM15, YTHDC1, YTHDC2, CBLL1, and RBMX) were selected as the candidate genes for predicting the risk of epilepsy." (PMID 36468034, 2022). "Firstly, we analyzed the expression of 17 m6A-related genes extracted from a public dataset and found that seven of them (HNRNPC, WTAP, RBM15, YTHDC1, YTHDC2, CBLL1, and RBMX) were differentially expressed between patients with epilepsy and healthy individuals." (PMID 36468034, 2022).
head and neck cancer (1 paper, 2021). A primary or metastatic malignant neoplasm affecting the head and neck. "It was found that head and neck cancer samples with high expression of writer genes KIAA1429 were in positive correlation with eraser genes ALKBH3 and FTO, while tumors with a high expression of writer genes (RBM15, RBM15B, and CBLL1) exhibited a low expression of eraser genes (ALKBH3 and FTO)." (PMID 35198565, 2021).
osteoarthritis (1 paper, 2021). A noninflammatory degenerative joint disease occurring chiefly in older persons, characterized by degeneration of the articular cartilage, hypertrophy of bone at the margins and changes in the synovial membrane. "There are no related researches about CBLL1 in cytokine signalling and immune regulations, but it has been reported METTL3 depletion enhanced proinflammatory cytokine expression in osteoblast and METTL3 promotes cytokine inflammatory response of osteoarthritis." (PMID 33724691, 2021).
osteomyelitis (1 paper, 2022). An acute or chronic inflammation of the bone and its structures due to infection with pyogenic bacteria. "In the m6A regulators-associated molecular subtypes, METTL3, CBLL1 and LRPPRC were significantly more highly expressed in subgroup A osteomyelitis than in subgroup B, while RBM15B and YTHDC1 expression were higher in subgroup A osteomyelitis." (PMID 36544487, 2022). "Based on the 6 significant m6A regulators with differential expression in the dataset, we further validated the expression of the 6 m6A regulators (METTL3, YTHDC1, YTHDF2, RBM15B, LRPPRC and CBLL1) in 10 osteomyelitis samples and 10 control samples by qRT‒PCR analysis." (PMID 36544487, 2022). "The qRT‒PCR results showed that the mRNA expression of METTL3, YTHDC1, RBM15B, LRPPRC and CBLL1 in osteomyelitis tissues was significantly increased, while that of YTHDF2 was significantly decreased (p < 0.05), which was consistent with the results of bioinformatics analysis." (PMID 36544487, 2022). "Visualization of the results by boxplot and heatmap suggested that the 5 regulators were differentially expressed between the two m6A subtypes, with METTL3, CBLL1 and LRPPRC highly expressed in cluster A osteomyelitis, RBM15B and YTHDC1 highly expressed in cluster B osteomyelitis." (PMID 36544487, 2022).
osteoporosis (1 paper, 2025). A condition of reduced bone mass, with decreased cortical thickness and a decrease in the number and size of the trabeculae of cancellous bone (but normal chemical composition), resulting in increased fracture incidence. "Additionally, other research has highlighted FTO, YTHDF2 and CBLL1 as diagnostic biomarkers and m6A‐related molecular patterns in osteoporosis." (PMID 39779466, 2025). "A study involving 80 women with varying BMD analysed differences in the expression levels of the major m6A regulators, leading to the identification of four potential biomarkers for osteoporosis diagnosis: METTL16, CBLL1, YTHDF2 and FTO." (PMID 39779466, 2025).
prostate adenocarcinoma (1 paper, 2022). "A comparative analysis of genetic alterations in METTL3, METTL14, WTAP and CBLL1 in primary prostate adenocarcinoma and metastatic PCa patients was undertaken." (PMID 36733939, 2022). "Expression and sub-cellular localisation of METTL3, METTL14, WTAP and CBLL1 were confirmed using IHC in both non-malignant and primary prostate adenocarcinoma specimens." (PMID 36733939, 2022).
Wilms tumor (1 paper, 2021). An embryonal neoplasm characterized by the presence of epithelial, mesenchymal, and blastema components. "Five of seven proven candidates, PEG10, YEATS2, FOXK1, CBLL1 and MCRS1 showed a clear positive correlation of mRNA levels with MYCN in Wilms tumors undergoing the SIOP protocol." (PMID 34689785, 2021).